DLL3 (delta like canonical Notch ligand 3)
Description:
Inhibits primary neurogenesis. May be required to divert neurons along a specific differentiation pathway. Plays a role in the formation of somite boundaries during segmentation of the paraxial mesoderm (By similarity).
Synonyms: SCDO1
Tractability: Antibody: UniProt predicts a signal peptide or a membrane-spanning region; its Gene Ontology location is reachable by antibodies, with medium confidence; the Human Protein Atlas places it where antibodies can reach. PROTAC: UniProt records ubiquitination sites on it. Other modalities: a drug acting on it is in phase 2 or 3 trials.
Gene: Protein-coding gene on chromosome 19 (39,498,895 to 39,508,481, forward strand). Ensembl gene ENSG00000090932.
Subcellular location: Membrane
Subcellular location (Human Protein Atlas): Nucleoplasm; Golgi apparatus; Plasma membrane
Pathways (Reactome):
Developmental Biology: Formation of paraxial mesoderm; Somitogenesis
Gene Ontology:
Molecular function: Notch binding; calcium ion binding
Biological process: skeletal system development; negative regulation of Notch signaling pathway; Notch signaling pathway
Cellular component: membrane; plasma membrane
Genetic constraint (gnomAD): Loss-of-function variants: 50 observed, 41.85 expected, observed/expected ratio (o/e) 1.19, 90% interval 0.95 to 1.51. The synonymous counts are far from expectation, so gnomAD's model fits this gene poorly and the ratio says little. Missense variants: 962 observed, 713.16 expected, observed/expected ratio (o/e) 1.35, 90% interval 1.28 to 1.42. Synonymous variants: 421 observed, 313.52 expected, observed/expected ratio (o/e) 1.34, 90% interval 1.24 to 1.46.
Homologues: Orthologues: chimpanzee DLL3 (98% identical), macaque DLL3 (96% identical), pig DLL3 (89% identical), dog DLL3 (89% identical), rabbit DLL3 (87% identical), mouse Dll3 (83% identical), rat Dll3 (82% identical), guinea pig DLL3 (80% identical), tropical clawed frog dlk2 (21% identical), Caenorhabditis elegans apx-1 (17% identical), Caenorhabditis elegans T25C12.3 (15% identical), Caenorhabditis elegans ZK1193.2 (14% identical), and 5 more. Paralogues in human: DLK2 (21% identical), CD93 (19% identical), WIF1 (16% identical), CD248 (15% identical), FBLN7 (14% identical), CRELD1 (13% identical), CRELD2 (12% identical), CLEC14A (10% identical).
Diseases named in the same sentence as DLL3 in open-access papers:
DLL3 is named in the same sentence as 106 diseases in open-access papers, as found by Europe PMC text mining. Sharing a sentence is not in itself a finding about the gene and the disease. The quoted sentences say what the papers report.
small cell lung carcinoma (70 papers, 2015 to 2026). Small cell lung cancer (SCLC) is a highly aggressive malignant neoplasm, accounting for 10-15% of lung cancer cases, characterized byrapid growth, and early metastasis. "Chimeric antigen receptor-T cells (CAR-T) based on circRNA encoding the anti-Delta-like Ligand 3 (DLL3) show enhanced efficacy toward small cell lung cancer (SCLC) compared to CAR-T cells based on mRNA." (PMID 40710359, 2025). "Recent advances have highlighted delta-like ligand 3 (DLL3) as a promising diagnostic and therapeutic target in NEPC (and similarly in small-cell lung cancer)." (PMID 41573423, 2025). "Delta-like 3 (DLL3) is an oncogenic protein aberrantly expressed in several tumors, particularly in small-cell lung cancer." (PMID 40284515, 2025). "Building on this, we optimized the electroporation conditions and employed a circRNA-electroporation strategy to engineer CAR-T cells targeting Delta-like ligand 3 (DLL3), a prominent target in small cell lung cancer (SCLC)." (PMID 40075480, 2025). "For example, Tarlatamab is an FDA-approved BiTE that binds to the major TCR co-receptor CD3 while spanning to bind to the DLL3 antigen on small cell lung cancer cells." (PMID 41479781, 2025). "DLL3 expression enhances the invasive and migratory properties of small-cell lung cancer (SCLC) in preclinical models." (PMID 39858036, 2025). "DLL3 has been identified as a distinctive cell surface marker exclusive to neuroendocrine cancers, observed in small cell lung cancer (SCLC)." (PMID 40849468, 2025). "Recently, therapies targeting DLL3 have shown clinical efficacy in aggressive NENs, including small cell lung cancers and neuroendocrine prostate cancers." (PMID 39874041, 2025). "Validation through qRT-PCR in 30 MTCs demonstrated upregulation of ASCL1, DLL3, and SOX2 in high-grade MTCs, a gene signature akin to small-cell lung carcinoma, molecular subgroup A. Subsequently, DLL3 expression was validated by immunohistochemistry." (PMID 38958823, 2024). "Certainly, the recent approval of Tarlatamab, the first BiTE for solid tumors targeting DLL3, a protein found in small cell lung cancer and in pancreatic cancer, opens the possibility of future studies of this BiTE in PaCa." (PMID 39759138, 2024). "Delta-like ligand 3 (DLL3) is an inhibitory Notch ligand and is upregulated on neuroendocrine tumours such as small cell lung cancer." (PMID 36831514, 2023). "DLL3 has been described to exhibit pro-carcinogenic action in small cell lung cancer, breast cancer, pituitary tumor and acute myeloid leukaemia, but an anti-cancer effect in hepatocellular carcinoma, and glioma." (PMID 37274780, 2023). "In other tumors like small-cell lung cancer, DLL3 is upregulated and maintains growth and neuroendocrine differentiation." (PMID 37893184, 2023). "Regarding small cell lung cancer treatment, an attractive target is represented also by delta-like 3 (DLL3)." (PMID 36831396, 2023). "There is also an ongoing clinical trial of CAR NK cells targeted against DLL3 in patients with small cell lung cancer (NCT05507593, accessed on 8 January 2023)." (PMID 36831514, 2023). "Only one study in small-cell lung cancer showed a correlation between DLL3 and PD-L1 expression that supports our results." (PMID 37893184, 2023). "Currently in phase III clinical trials, Rovalpituzumab tesirine (Rova-T; SC16LD6.5) is a biomarker-specific ADC for the exclusive targeting small-cell lung cancers expressing Delta-like protein 3 (DLL3) antigen." (PMID 35214128, 2022). "DLL3 mRNA was differentially overexpressed in neuroblastoma at comparable levels to small cell lung cancer, as well as Wilms and rhabdoid tumors." (PMID 36381237, 2022). "Neuroblastomas have neuroendocrine features and often show similar gene expression patterns to small cell lung cancer including high expression of delta-like ligand 3 (DLL3)." (PMID 36381237, 2022).
small cell lung carcinoma (continued). "This first-in-class anti-DLL3-ADC showed promising results in a phase I study of antitumor activity in patients with recurrent small-cell lung carcinoma (SCLC) that exhibit high DLL3 expression (NCT01901653)." (PMID 36010607, 2022). "Delta-like ligand 3 (DLL3) is particularly upregulated in small cell lung cancer (SCLC) but with minimal normal tissue expression." (PMID 34039409, 2021). "Delta-like ligand 3 (DLL3) is an inhibitory Notch ligand that is minimally expressed in normal tissues but always specially and highly expressed on the surface of small cell lung cancer (SCLC) cells and other high-grade neuroendocrine tumor cells." (PMID 34425876, 2021). "Delta-like protein 3 (DLL3) is a potential therapeutic target molecule for small cell lung cancer (SCLC) and other neuroendocrine tumors that is minimally expressed in normal tissues." (PMID 34064074, 2021). "UWG01CTC showed a higher expression of DLL-3, which is known to be expressed on most high grade neuroendocrine cancers, particularly small cell lung cancer." (PMID 31953491, 2020). "The Notch ligand DLL3 has emerged as a novel therapeutic target in small cell lung cancer and high-grade neuroendocrine carcinomas." (PMID 31508369, 2019). "Tarlatamab is a first-in-class, half-life extended bispecific antibody delta-like ligand 3 (DLL3)-directed CD3 T cell engager indicated for the treatment of adult patients presenting advanced stage small cell lung cancer (ES-SCLC) with disease progression during or after platinum-based chemotherapy." (PMID 40868216, 2025). "Targeting DLL3 which are expressed on the surface of small cell lung cancer tumor cells." (PMID 41181137, 2025). "Constructs targeting well-defined tumor-associated antigens such as HER2, DLL3, PSMA, CEA, and EGFRvIII have entered advanced clinical trials across a variety of solid tumor types, including breast cancer, small cell lung cancer (SCLC), prostate cancer, and glioblastoma." (PMID 40508128, 2025). "However, DLL3 is selectively expressed in the cell surface of specific tumors, especially in small-cell lung cancer (SCLC) and neuroendocrine tumors." (PMID 40284515, 2025). "Notably, DLL3, an inhibitory Notch ligand, has shown aberrant expression on the surface of small cell lung cancer (SCLC) and high-grade neuroendocrine tumors or small cell cancer outside the lung." (PMID 39272956, 2024). "Delta-like ligand 3 (DLL3) has been reported to be overexpressed in small cell lung cancer (SCLC) and may be a rational target for CAR-NK immunotherapy." (PMID 39415291, 2024). "However, several studies showed that DLL3 is highly expressed in small cell lung carcinoma (SCLC) and other neuroendocrine cells neoplasm, which offers potential for DLL3-targeted therapeutic design." (PMID 37179118, 2023). "In addition, DLL3 was highly expressed in many cancers and elevation of DLL3 enhanced the development of many cancers, including small-cell lung cancers, pituitary adenomas, breast cancer, and acute myeloid leukemia." (PMID 35382168, 2022). "Novel targets such as Bcl-2, VEGF, and delta-like protein 3 (DLL3) are currently being investigated in small cell lung cancer, which, if successful, may be applied to non-small-cell lung cancers." (PMID 26823665, 2015). "Moreover, elevated DLL3 could exacerbate the progression of many cancers including small-cell lung cancer and pituitary adenoma." (PMID 35382168, 2022). "In small cell lung cancer (SCLC), biomarkers such as NSE and DLL3 have emerged as targets for antibody-drug conjugates and immune-based therapies like Tarlatamab." (PMID 41008611, 2025). "(DLL3 is a Notch ligand that) plays a role in neuroendocrine differentiation and SCLC (Small Cell Lung Cancer) tumorigenesis." (PMID 40700292, 2025). "In small cell lung cancer (SCLC), altered DLL3 expression has a notable impact on patient survival outcomes." (PMID 40066092, 2025).
small cell lung carcinoma (continued). "In a similar approach targeting small cell lung cancer (SCLC), researchers investigated the therapeutic potential of CAR-engineered NK-92 cells directed against delta-like ligand 3 (DLL3)." (PMID 38694508, 2024). "So far, only a limited number of studies investigated and confirmed the detection of DLL3 expression in CTCs of CRPC and small cell lung cancer patients." (PMID 39550585, 2024). "DLL3 is an inhibitory ligand of NOTCH signaling that is highly upregulated and aberrantly expressed on the cell surface of small-cell lung cancer (SCLC) and other high-grade neuroendocrine tumors as a key driving gene." (PMID 35332121, 2022). "In small cell lung cancer (SCLC), DLL3 is highly expressed in more than 80% of patients and is highly expressed in both the cell membrane and cytoplasm of the tumor." (PMID 36338696, 2022). "DLL3, a non-canonical inhibitor of the Notch signaling pathway, exhibits unique molecular mechanisms that underpin its dual role in small cell lung cancer (SCLC) progression and therapeutic targeting." (PMID 40496850, 2025). "Recent advances in the molecular characterization of small-cell lung cancer (SCLC) have led to the identification of distinct transcriptional subtypes, defined by the differential expression of surface antigens such as SEZ6, DLL3, B7-H3 (CD276), TROP2 (TACSTD2), and CEACAM5." (PMID 41149456, 2025). "A new clinical trial using DLL3-directed chimeric antigen receptor T-cells in patients with extensive stage small cell lung cancer (NCT05680922) has also been listed but not yet recruiting." (PMID 38659003, 2024). "An Amgen-sponsored Phase 1 study of AMG 119 CAR T-cells targeted against DLL3 in small cell lung cancer was suspended with no patients enrolled (NCT03392064; posted November 2022, accessed on 8 January 2023)." (PMID 36831514, 2023). "Furthermore, DLL3 expression is more abundant in neoplastic cells, especially in small-cell lung cancer and other neuroendocrine neoplasms, as opposed to healthy cells where they do not exert any expression except for in the testis and central nervous system." (PMID 37893184, 2023). "Rovalpituzumab tesirine, an anti-DLL3 PBD-conjugated ADC, showed modest antitumor activity in patients with small-cell lung carcinoma treated in third lines (NCT02674568), but such anti-DLL3 ADCs could represent a potential strategy for treating viro-positive MCCs." (PMID 35159045, 2022). "Delta-like protein 3 (DLL3) is a protein of the Notch pathway, and it is a potential therapeutic target for high-grade lung neuroendocrine tumors (NETs), i.e., small cell lung carcinoma (SCLC) and large cell neuroendocrine carcinoma (LCNEC)." (PMID 34568063, 2021).
glioma (30 papers, 2010 to 2025). A benign or malignant brain and spinal cord tumor that arises from glial cells (astrocytes, oligodendrocytes, ependymal cells). "Further exploring the association between DLL3 expression and the anatomic site of origin, we find a rather consistent trend of tumors derived from the neural crest, such as gliomas and melanomas representing cancers with relatively robust DLL3 expression." (PMID 39874041, 2025). "Further corroborating these patterns, however, are the associations we found with high DLL3 and better overall survival in low-grade and high-grade gliomas." (PMID 39874041, 2025). "These considerations highlight that DLL3 inhibition may be a favorable therapeutic strategy for the cure of glioma with IDH mutation." (PMID 34425876, 2021). "Despite uniform DLL3 expression in IDH-mutant gliomas, therapeutic exploitation remains constrained by blood-brain barrier impermeability and NOTCH pathway redundancy." (PMID 40496850, 2025). "C6 DLL3+ Glioma cells are involved in RNA splicing, mRNA processing, and ribonucleoprotein complexes." (PMID 39403379, 2024). "DLL3 has been shown to have anticarcinogenic effects in glioma, hepatocellular carcinoma and malignant glioma, but procarcinogenic effects in SCLC, pituitary tumors, and acute myeloid leukemia." (PMID 37179118, 2023). "This study showed that DLL3 expression was associated with TMB in 12 different tumor types, including breast, colorectal, lungs, glioma, and kidney cancer." (PMID 37179118, 2023). "mIDH1 gliomas with high expression of DLL3 showed increased immune infiltration, suggesting an association between Notch signaling and immune activity in these tumors." (PMID 36647827, 2023). "DLL3 is an inhibitory Notch ligand, and its expression positively correlated with survival in mIDH1 gliomas." (PMID 36647827, 2023). "The Notch pathway was shown to be epigenetically modulated in mIDH1 gliomas, through DNA methylation of CpG sites within the delta-like ligand 3 (DLL3) gene." (PMID 36647827, 2023). "The cell surface Notch ligand delta-like 3 (DLL3) inhibits Notch pathway activation and has shown to be expressed on the cell surface of several tumor types including gliomas where DLL3 expression inversely correlated with outcome." (PMID 34926242, 2021). "Our analysis suggested that Notch signaling pathway (including key genes METTL3, DLL3, HES1, and NOTCH3) closely implicated with tumorigenesis and cancer development was found to be involved in glioma." (PMID 34589481, 2021). "This suggests that DLL3 may serve as a subtype-specific biomarker in gliomas, with implications for patient stratification." (PMID 40284515, 2025). "Besides, in mIDH1-mutant gliomas, epigenetic modulation of the Notch signaling cascade is achieved through DNA methylation at CpG dinucleotides within the delta-like ligand 3 (DLL3) genomic locus." (PMID 40927709, 2025). "In addition to SCLC, DLL3 is overexpressed in other tumor cells, such as stomach cancer cells, isocitrate dehydrogenase-mutant glioma, gastrointestinal neuroendocrine cancer, small-cell bladder cancer, and some types of breast cancer." (PMID 40284515, 2025). "Aggregating a cohort of 203,252 tumor samples across 47 cancer types, we found upregulation of DLL3 in the majority of low-grade gliomas (78%), high-grade gliomas (72%), Merkel cell carcinomas (83%), medulloblastomas (69%), and melanomas (43%), in conjunction with SCLCs (89%) and NETs (49%)." (PMID 39874041, 2025). "DLL3 is expressed on a wide variety of neuroendocrine cancers, including high-grade neuroendocrine cancers of the lung, prostate, breast, pancreas, and intestinal tract as well as low-grade glioma and neuroblastoma." (PMID 36951942, 2023). "Finally, IDHmt glioma cells have been shown to specifically exhibit greater levels of Notch ligand delta-like 3 (DLL3) RNA and were sensitive to anti-DLL3 antibodies." (PMID 36831683, 2023).